B4GALT1 (beta-1,4-galactosyltransferase 1)
Diseases named in the same sentence as B4GALT1 in open-access papers (continued):
Sharing a sentence is not in itself a finding about the gene and the disease.
B4GALT1 also shares sentences with these, for which no sentence is quoted: cardiovascular disease (2 papers); Peters plus syndrome (2); renal carcinoma (2); asthma (1); bacterial infections (1); cognitive decline (1); congenital disorder of glycosylation (1); Congenital disorder of glycosylation, type IId (1); Crohn disease (1); cystadenoma (1); endometrial cancer (1); galactosaemia (1); hearing loss (1); idiopathic pulmonary fibrosis (1); leukocytosis (1); lymph node metastasis (1); memory impairment (1); microcephaly (1); myeloproliferative neoplasm (1); neurologic disease (1); osteosarcoma (1); systemic lupus erythematosus (1).